RBM10 (RNA binding motif protein 10)
Description:
Binds to ssRNA containing the consensus sequence 5'-AGGUAA-3'. May be involved in post-transcriptional processing, most probably in mRNA splicing. Binds to RNA homopolymers, with a preference for poly(G) and poly(U) and little for poly(A) (By similarity). May bind to specific miRNA hairpins. Acts as a late-stage inhibitor of pre-60S ribosome assembly by preventing pre-60S ribosome export from nucleus.
Synonyms: MINAS-60; S1-1; DXS8237E; GPATC9; GPATCH9; KIAA0122; ZRANB5; TARPS
Tractability: PROTAC: ubiquitination databases record sites on it; its protein half-life has been measured.
Gene: Protein-coding gene on chromosome X (47,144,284 to 47,186,814, forward strand). Ensembl gene ENSG00000182872.
Subcellular location: Nucleus, nucleolus; Nucleus
Subcellular location (Human Protein Atlas): Nuclear speckles
Pathways (Reactome):
Metabolism of RNA: Processing of Capped Intron-Containing Pre-mRNA; mRNA Polyadenylation; mRNA Splicing - Major Pathway
Disease: Dengue virus activates/modulates innate and adaptive immune responses
Gene Ontology:
Molecular function: identical protein binding; miRNA binding; protein binding; RNA binding; nucleic acid binding
Cellular component: nuclear speck; nucleus; protein-containing complex; nucleoplasm
Gene-disease validity (ClinGen):
ClinGen rates the evidence that RBM10 causes each of these diseases.
TARP syndrome (X-linked): Definitive. A rare developmental defect during embryogenesis syndrome characterized by Robin sequence (micrognathia, glossoptosis, and cleft palate), atrial septal defect, persistence of the left superior vena cava, and talipes equinovarus.
Cancer hallmarks: escaping programmed cell death; suppression of growth (promotes)
Homologues: Orthologues: macaque RBM10 (99% identical), dog RBM10 (98% identical), rabbit RBM10 (98% identical), pig RBM10 (98% identical), chimpanzee RBM10 (98% identical), guinea pig RBM10 (98% identical), rat Rbm10 (97% identical), mouse Rbm10 (96% identical), zebrafish rbm10 (47% identical), Drosophila melanogaster CG4896 (30% identical), Drosophila melanogaster CG4887 (29% identical), Caenorhabditis elegans rbm-5 (25% identical). Paralogues in human: RBM5 (48% identical), RBM6 (26% identical).
Diseases named in the same sentence as RBM10 in open-access papers:
RBM10 is named in the same sentence as 75 diseases in open-access papers, as found by Europe PMC text mining. Sharing a sentence is not in itself a finding about the gene and the disease. The quoted sentences say what the papers report.
lung carcinoma (34 papers, 2015 to 2025). "WES on five LUAD primary tumor–normal pairs from patients who later developed brain metastasis showed that truncating mutations in RBM10 occur in patients with lung cancer brain metastases." (PMID 40069781, 2025). "IHC analysis showed that RBM10 expression was associated with brain metastasis in lung cancer patients with EGFR mutations; the low expression group had a higher rate of brain metastasis." (PMID 40069781, 2025). "Our findings uncover RBM10 as a pivotal c-Myc repressor by cooperating with uL18 and uL5 in lung cancer cells, as its failure to do so upon mutation favors tumorigenesis." (PMID 38032932, 2023). "The mutation of RBM10 co-exists with the known lung cancer target genes KRAS, EGFR, and PIK3CA, among others." (PMID 37509501, 2023). "RBM10 is an RNA-binding protein frequently deleted or mutated in lung cancers as well as other types of cancers (20, –22) and even homozygously deleted (Homdel) in some cancers." (PMID 38032932, 2023). "We queried a database of a distinct UCSF-based cohort to identify patients with EGFR-mutant lung cancer whose tumors harbored co-occurring RBM10 mutations." (PMID 35579943, 2022). "Mutations in RBM10 that decreased its expression are most commonly associated with LUAD, while the overexpression of RBM10 can inhibit lung cancer cell proliferation." (PMID 33718153, 2021). "Missense or truncating RBM10 mutations found in lung cancer patients were shown to disrupt RBM10-mediated splicing regulation of the Notch pathway regulator NUMB." (PMID 34065983, 2021). "For example, as regulators of alternative splicing of apoptotic genes, RBM5, RBM6 and RBM10 are frequently deleted or mutated in lung cancer." (PMID 34398362, 2021). "Higher expression of RBM10 protein in tissue samples of lung cancer patients was reported associated with poor prognosis." (PMID 33479213, 2021). "For example, recent researches revealed that high expression of RBM10 protein in lung cancer was associated with a shorter overall survival time and a poor prognosis." (PMID 32098099, 2020). "Recently, RBM10 was identified as one of the most frequently mutated genes in lung cancer and RBM10 mutations have been linked to pancreatic cancer and colorectal carcinoma." (PMID 28379442, 2017). "Experiments using CellTracker Green (CFMDA)-labeled cells suggested that co-mutation of EGFR and RBM10 could promote brain metastasis in lung cancer cells." (PMID 40069781, 2025). "Similarly, mutations in the splicing factor RBM10 lead to increased exon 9 inclusion in Numb which promotes lung cancer cell growth." (PMID 40241749, 2025). "Our previous research demonstrated a link between RBM10 deficiency and lung cancer metastasis." (PMID 40069781, 2025). "The findings of this study suggest that targeting S1P, which is regulated by RBM10, could be a promising therapeutic strategy for patients with lung cancer associated with RBM10 deficiency." (PMID 40069781, 2025). "Building on this foundation, we hypothesize that RBM10 influences BBB permeability in EGFR-mutated lung cancer by regulating sphingolipid metabolism." (PMID 40069781, 2025). "For example, mutations in the splicing regulator RBM10 promote exon 9 inclusion in the Notch signaling inhibitor numb transcript, giving rise to an alternative protein isoform that stimulates Notch pathway activation and proliferation in lung cancer." (PMID 39034402, 2024). "We reasoned that loss-of-function genetic alterations in RBM10 that dampen the apoptotic response to EGFR inhibitor therapy could enhance cancer cell survival in patients with EGFR-mutant lung cancer." (PMID 35579943, 2022). "Here, we investigated the open question of whether and how mutations in splicing factors such as RBM10 contribute to lung cancer pathogenesis or modulate sensitivity to oncoprotein-targeted kinase inhibitor therapy." (PMID 35579943, 2022).
lung carcinoma (continued). "Consistent with these clinical data, other investigators observed early clinical progression associated with decreased sensitivity to EGFR TKI therapy in a patient with EGFRL858R lung cancer whose tumor also harbored a clonal co-occurring truncating RBM10 mutation." (PMID 35579943, 2022). "Similar to lung cancer, the majority of RBM10 mutations (63.6%) in CCA truncate the protein and may alter downstream splicing of specific genes." (PMID 35650238, 2022). "Due to their similarity and recent evidence that RBM10 mutates in up to 21% of lung cancer, majority of studies hypothesized that RBM10 has the tumor suppressive properties of RBM5 in small cell lung cancer." (PMID 33718153, 2021). "An analysis of data from the HCMDB database, which included 77 lung cancer patients, revealed that among 14 patients with lung adenocarcinoma, 6 developed brain metastases with reduced RBM10 expression." (PMID 40069781, 2025). "Our previous study revealed that RBM10 inhibits LUAD progression by regulating the Wnt/β-catenin signaling pathway, and RBM10 deficiency is associated with lung cancer metastasis, especially brain metastasis." (PMID 40069781, 2025). "As a result, RBM10-I316F significantly promoted proliferation of lung cancer cells and the growth of the cells-derived xenograft tumors in mice." (PMID 38032932, 2023). "Previously, RBM10-I316F was shown to lose its ability to suppress proliferation of cultured lung cancer A549 cells." (PMID 38032932, 2023). "Here, we show that wild-type RBM10 suppresses lung cancer cell growth and proliferation by inactivating c-Myc that is essential for cancer cell survival." (PMID 38032932, 2023). "Clinical impact of RBM10 downregulation in advanced-stage EGFR-mutant lung cancer treated with an EGFR TKI." (PMID 35579943, 2022). "Thirdly, in lung cancer RBM10 is highly expressed, but while in our A549, HeLa, BEAS-2B and GLC20 cells transcripts encoding both RBM10v1 isoforms were observed, there was two-fold more RBM10v1(V354del) than RBM10v1(V354) in the GLC20 SCLC cells." (PMID 25889998, 2015). "Given that GALC plays an important role in brain metastasis of lung cancer, we next investigated whether RBM10 has a pro-brain metastasis function through its influence on the sphingolipid metabolic pathway." (PMID 40069781, 2025). "It has been reported that as a tumor suppressor gene, RBM10 can also promote lung cancer." (PMID 38803537, 2024). "RBM5 and RBM10 were determined as a tumor suppressor in lung cancer progression." (PMID 39741300, 2024). "To illustrate which domain(s) or amino acid(s) of RBM10 would be a key for its suppression of c-Myc activation through uL18 and uL5, we employed the lung cancer–derived mutant RBM10-I316F, which markedly increased lung adenocarcinoma (LUAD) A549 cell proliferation in cell culture." (PMID 38032932, 2023). "Interestingly, RBM10 still reduced c-Myc protein levels even when lung cancer cells were treated with Isoginkgetin, a small molecule inhibitor of pre-mRNA splicing." (PMID 38032932, 2023). "To assess whether RBM10 expression could modulate apoptosis in EGFR-mutant lung cancer, we first assessed cleavage of the apoptotic biomarker poly (ADP-ribose) polymerase (PARP) in H3255 (EGFR L858R/RBM10 WT) and PC-9 (EGFR del19/RBM10 WT) cells." (PMID 35579943, 2022). "Clinicogenomic validation of mutant RBM10 in EGFR-mutant lung cancer." (PMID 35579943, 2022).
lung carcinoma (continued). "In recent years, several articles have reported the regulation of RBM10 in lung cancer." (PMID 36335386, 2022). "Although there are conflicting conclusions about whether this protein promotes or inhibits lung cancer, most of the experimental results confirmed that RBM10 is a tumor suppressor factor." (PMID 36335386, 2022). "Most of the experiments in lung cancer considered RBM10 could promote apoptosis and inhibit proliferation." (PMID 33718153, 2021). "RBM10 overexpression suppresses lung cancer cell proliferation." (PMID 34804951, 2021). "However, in the majority of the reports, RBM10 is still considered to play an anti-cancer role, with only a few suggesting it promotes the development of lung cancer." (PMID 33718153, 2021). "Several studies have indicated that RBM10 could suppress lung cancer progression by controlling alternative splicing of other genes." (PMID 34367963, 2021). "For example, RBM10 undergoes frameshifts, truncations, and indels in lung cancer similar to our findings in UM28, suggesting that oncogenic mechanisms may vary among different splicing factor mutations." (PMID 29317634, 2018). "Here, we reported that RBM10 acts as a regulator of c-Myc to reduce c-Myc stability and activity by partnering with the two ribosomal proteins uL18 and uL5, consequently suppressing the proliferation of human lung cancer cells and the growth of their xenograft tumors." (PMID 38032932, 2023). "An additional area of investigation includes the role of RBM10 deficiency in lung cancer pathogenesis in the absence of systemic therapy, given the differential findings observed in this treatment-naive context in the human systems in our study versus recent data in murine models." (PMID 35579943, 2022). "Therefore, it is one of our research directions to determine whether RBM10 regulates the AS of Neat1 to affect the occurrence and development of lung cancer." (PMID 36335386, 2022). "Therefore, we still maintain that RBM10 is a tumor suppressor that plays a role in lung cancer." (PMID 33718153, 2021). "NUMB is the most studied downstream effector of RBM10, and dysregulation of NUMB AS is frequently found in lung cancer." (PMID 36335386, 2022). "SFs, including QKI, RBM4, RBM5, RBM6, RBM10, and SRSF1, were involved in the development of lung cancer, as SFs play a regulatory role in splicing." (PMID 33047900, 2020). "Consequently, RBM10 may also hold prognostic potential for assessing SCLC risk and provide important information regarding the development and/or progression of this particularly aggressive form of lung cancer." (PMID 28662214, 2017). "Through alternative splicing of GALC, RBM10, as a splicing factor, downregulates GALC expression, leading to decreased S1P concentration and subsequent inhibition of brain metastasis formation in lung cancer." (PMID 40069781, 2025). "Strongly supporting this, the lung cancer–derived RBM10 mutant, RBM10-I316F, fails to bind to uL18 or uL5, to suppress c-Myc activity, and thus to inhibit lung cancer growth." (PMID 38032932, 2023). "Taken together, these results demonstrate that wild-type RBM10, but not RBM10-I316F, can inhibit c-Myc expression and activity, consequently suppressing the proliferation and growth of lung cancer cell and tumorigenesis." (PMID 38032932, 2023). "In addition, in BRCA, COAD, TGCT, KIRC, LIHC, lung cancer, ESCA, OV, and SKCM, the expression of RBM10 in metastatic tumor tissues was markedly increased in comparison with that in the corresponding primary tumor tissues." (PMID 39282149, 2022). "In addition, previous studies have shown that RBM10 regulates the phosphorylation of the RAP1/AKT/CREB and MAPK/PI3K/AKT signaling pathways in lung cancer." (PMID 36335386, 2022). "Since there is no known functional impact of RBM10 on EGFR-mutant lung cancer treatment, we tested the hypothesis that RBM10 inactivation may modulate EGFR TKI sensitivity in EGFR-mutant LA." (PMID 35579943, 2022).
lung carcinoma (continued). "As for the genetic landscape in detail, several incidences of mutated genes that were adverse to prognosis were observed to be lower in the young lung cancer group (LRP1B, SMARCA4, STK11, FAT2, RBM10, FANCM), which may explain the better prognosis of the young lung cancer group to some extent." (PMID 35096611, 2021). "Additionally, EGFR, MGA, SMARCA4, ATM, RBM10 and KDM5C which are lung cancer related genes are mutated only in LUAD but not in LUSC." (PMID 33672117, 2021). "This study reveals that the tumor suppressor RBM10 works with ribosomal proteins and acts to inhibit the oncogenic activity of c-Myc, whereas a lung cancer–derived RMB10 mutant fails to do so; instead, it promotes lung cancer growth." (PMID 38032932, 2023).
lung adenocarcinoma (30 papers, 2013 to 2026). A carcinoma that arises from the lung and is characterized by the presence of malignant glandular epithelial cells. "RBM10, a splicing regulator frequently mutated in lung adenocarcinoma (LUAD), modulates RNA processing, but its involvement in circRNA regulation has not yet been addressed." (PMID 41673707, 2026). "RBM10 expression is downregulated in lung adenocarcinoma (LUAD) and is significantly associated with tumor cell proliferation and apoptosis." (PMID 40069781, 2025). "To further investigate the role of RBM10 in brain metastases, we collected clinicopathological data from 23 lung adenocarcinoma patients with EGFR mutations." (PMID 40069781, 2025). "Loss of function mutations in RBM10 identified in lung adenocarcinoma disrupt RBM10 function leading to increased exon 9 inclusion, and increased proliferation of the lung adenocarcinoma derived A549 cell line." (PMID 39863103, 2025). "RNA-binding motif protein 10 (RBM10) encodes an RNA-binding protein involved in the regulation of splicing, and is mutated at a high frequency in a variety of tumors, especially lung adenocarcinoma." (PMID 38431575, 2024). "RNA-binding motif protein 10 (RBM10) is a frequently mutated tumor suppressor in lung adenocarcinoma (LUAD)." (PMID 38032932, 2023). "Survival curve analysis was performed on the clinical group data of lung adenocarcinoma patients with GS and GU classification of RBM10 and wild-type mutations." (PMID 37509501, 2023). "A related study performed exon and transcriptome sequencing on 98 lung adenocarcinoma precursor lesions and 99 invasive adenocarcinoma tissue specimens and identified RBM10 as a significantly mutated gene in the progression of lung adenocarcinoma." (PMID 37509501, 2023). "This also suggests that RBM10 is involved in the regulatory process for the mechanisms underlying resistance to targeted drugs for lung adenocarcinoma, which has important clinical significance for the effective survival of patients." (PMID 37509501, 2023). "Cancer and oncology genome mapping (CGA) showed that EGFR mutations were most common in female lung adenocarcinoma patients, while mutations in RNA-binding motif protein 10 (RBM10) were most common in male lung adenocarcinoma patients." (PMID 37509501, 2023). "Nomogram analysis was also used in this study, and the results also showed that SMAD9, KHDRBS2, and RBM10 had a certain risk correlation with the survival rate of lung adenocarcinoma patients." (PMID 37509501, 2023). "Recent studies have detected multiple truncated and missense mutations in RBM10 in lung adenocarcinoma, but the role of RBM10 in lung adenocarcinoma is unclear." (PMID 37509501, 2023). "In a subset of lung adenocarcinomas with mutations in the RBM10 gene, the mutations were localized in the splice sites causing the same exon skipping events that normally occur when RBM10 is wild type, resulting in much reduced RBM10 expression by NMD." (PMID 34065983, 2021). "This is well in line with the fact that RBM10 mutations are observed in a number of human cancers, such as lung adenocarcinoma, pancreatic, colorectal, and thyroid cancers." (PMID 32947864, 2020). "The Cancer Genome Atlas Research Network found that EGFR mutations are more frequent among female lung adenocarcinoma patients, whereas mutations in RNA‐binding motif protein 10 (RBM10) are more common among male patients." (PMID 30955253, 2019). "This is indeed the result seen in clinical samples; loss-of-function RBM10 mutations were associated with increased pathogenesis of lung adenocarcinomas." (PMID 28662214, 2017). "RBM10 is an RNA splicing regulator that is frequently mutated in lung adenocarcinoma (LUAD) and has recently been proposed to be a cancer gene." (PMID 28091594, 2017). "The RNA binding protein RBM10 was found to be significantly mutated in lung adenocarcinomas with recurring frameshift, nonsense, or splice site mutations." (PMID 24498085, 2014).